METTL14 (methyltransferase 14, N6-adenosine-methyltransferase non-catalytic subunit)
Diseases named in the same sentence as METTL14 in open-access papers (continued):
Sharing a sentence is not in itself a finding about the gene and the disease.
pancreatic cancer (continued). "In addition, two independent studies suggested that knockdown of METTL14 alone in pancreatic cancer enhanced sensitivity to cisplatin and gemcitabine." (PMID 41194259, 2025). "The expression of METTL14 is closely related to the survival of pancreatic cancer patients." (PMID 39289775, 2024). "Notably, m6A “writer” proteins, namely METTL3 and METTL14, have been identified as dysregulated factors in bladder, gastric, and pancreatic cancers." (PMID 38528591, 2024). "Silencing METTL14 increased the sensitivity of pancreatic cancer cells to gemcitabine." (PMID 37264402, 2023). "It was reported that METTL14 was up-regulated in gemcitabine-resistant pancreatic cancer cells." (PMID 36977668, 2023). "METTL14 downregulation could result in autophagy activation via the mTOR signaling pathway, thus effectively improving cisplatin sensitivity in pancreatic cancer cells." (PMID 36632456, 2023). "In this study, we clarified the effects of METTL14 on the metastasis of pancreatic cancer." (PMID 37215454, 2023). "Importantly, the retention of exon 10 in METTL14 leads to an elevation in global m6A content and accelerates metastasis in pancreatic cancer." (PMID 37850412, 2023). "In pancreatic cancer, METTL14 has been found to be involved in gemcitabine resistance." (PMID 36291811, 2022). "Another study elucidated the mechanism of METTL14 in drug resistance in pancreatic cancer." (PMID 34904301, 2022). "In addition, p65 regulated the gemcitabine resistance in pancreatic cancer via promoting the expression of METTL14." (PMID 36291811, 2022). "In addition, p65 bound the promoter area of METTL14, and regulated its expression in pancreatic cancer cells." (PMID 36291811, 2022). "We next wonder how METTL14 was regulated in gemcitabine resistant pancreatic cancer cells." (PMID 34458141, 2021). "Although the expression of METTL14 was increased in the resistant pancreatic cancer cells, the regulatory mechanism of expression remains unclear." (PMID 34458141, 2021). "Since METTL14 was found up-regulated in gemcitabine resistant pancreatic cancer cells, we hypothesis that METTL14 has functional role in chemoresistance." (PMID 34458141, 2021). "METTL14 could promote the growth and metastasis of pancreatic cancer by up regulating the m6A level of PERP mRNA." (PMID 34863142, 2021). "In the present study, we demonstrate that the expression of METTL14 was increased after gemcitabine treatment, and METTL14, but not other m6A associated proteins, was overexpressed in the gemcitabine resistant pancreatic cancer cell lines." (PMID 34458141, 2021). "Furthermore, the transwell assay revealed that PERP knockdown also significantly counteracted the METTL14 depletion-dependent inhibition of pancreatic cancer cells invasion ability." (PMID 32843065, 2020). "Additionally, also METTL14 should be considered, for the development of novel drugs targeting pancreatic cancer." (PMID 32843065, 2020). "Research demonstrated that the upregulation of METTL14 expression in pancreatic cancer cells could reduce the response to mTOR signal-mediated autophagy after cisplatin treatment." (PMID 32760220, 2020). "We then show that the dysregulation of METTL14 can affect m6A levels in pancreatic cancer cells." (PMID 32843065, 2020). "Importantly, since PERP is the major effector through which METTL14 promotes the growth of pancreatic cancer, we suggest it as a potential therapeutic target." (PMID 32843065, 2020). "However, little is known about the distinct expression patterns of these regulators, particularly METTL14, or their precise tumorigenic contributions for various malignancies, including pancreatic cancer." (PMID 32843065, 2020). "Furthermore, overexpression of METTL14 promoted pancreatic cancer growth." (PMID 40448344, 2025).
pancreatic cancer (continued). "Additionally, it was also reported that overexpression of METTL14 could significantly promote the proliferation and metastasis of pancreatic cancer cells in vitro and in vivo via targeting PERP in an m6A-dependent manner." (PMID 38326804, 2024). "In addition, inhibited exon skipping of METTL14 and enhanced exon skipping of Cyclin L2 caused by CLK1’s enhancing SRSF5 SRSF5250-Ser phosphorylation enhanced the N6-methyladenosine modification level and cancer aggressiveness in pancreatic cancer." (PMID 36977668, 2023). "Moreover, tumor location and ages of PC patients showed significant relevance to the expression of METTL14, which indicated METTL14 was closely related with tumor progression and could be utilized as a prognostic marker in pancreatic cancer." (PMID 37215454, 2023). "Moreover, upregulation of METTL14 promotes the growth and metastasis of pancreatic cancer." (PMID 34476213, 2021). "In addition, we constructed plasmids coding for PERP WT or PERP with a specific 3′-UTR site mutation (that does not prevent PERP expression) and evaluated their impact (after transfection) on the tumorigenic properties of pancreatic cancer cells overexpressing METTL14." (PMID 32843065, 2020). "The interplay between Mettl3, Mettl14, miR-380-3p, PTEN, and the AKT pathway sheds light on the regulatory mechanisms involved in pancreatic cancer progression." (PMID 41517663, 2026). "IGF2BP2 binds to METTL14 m6A‐modified TGFB2 mRNA and upregulates TGFB2 expression, resulting in enhanced gemcitabine resistance in pancreatic cancer." (PMID 40448344, 2025). "Upregulated METTL14 hampers the attenuation of cytidine deaminase (CDA) transcript, enhances its stability, and induces chemotherapy resistance of pancreatic cancer cells." (PMID 34904301, 2022). "For instance, METTL14 upregulation promotes PERP mRNA N6‐adenosine methylation, facilitating metastasis and growth in pancreatic cancer." (PMID 36264762, 2022). "Specifically, overexpressed METTL14 directly targets the downstream PERP mRNA to enhance propagation and migration of pancreatic cancer cells in an m6A‐dependent way." (PMID 34904301, 2022). "Previous studies reported that METTL3, METTL14, FTO, ALKBH5 and YTHDF2 play important roles in pancreatic cancer cells." (PMID 34458141, 2021). "We further provide evidence that METTL14 promotes the growth and metastasis of pancreatic cancer, and identify PERP as an important METTL14 target gene." (PMID 32843065, 2020). "Overall, mechanistically, METTL14 dysregulation leads to increased m6A modifications in the PERP 3′-UTR, promoting the growth and metastasis of pancreatic cancer." (PMID 32843065, 2020). "Our data suggest that the upregulation of METTL14 leads to the decrease of PERP levels via m6A modification, promoting the growth and metastasis of pancreatic cancer; therefore METTL14 is a potential therapeutic target for its treatment." (PMID 32843065, 2020). "These modifications can be written by METTL3 or METTL14 and can be erased by ALKBH5 and regulate the tumorigenesis of leukemia, pancreatic cancer, endometrial cancer and gastric cancer." (PMID 31722709, 2019). "The expression of METTL14 was higher in pancreatic cancer tissues than in non-tumor tissues, and knockdown of METT14 promoted apoptosis by reducing the expression levels of AMPKα, ERK1/2." (PMID 39289775, 2024). "For example, METTL14 is decreased in CRC and acts as a tumor suppressor to inhibit cancer cell proliferation, migration, and invasion, while its expression is increased in pancreatic cancer, serving as an oncogene to sustain the tumor growth and metastasis." (PMID 37015927, 2023).
pancreatic cancer (continued). "METTL3 and METTL14 in the m6A methyltransferase component are expected to become new targets for tumor radiotherapy and chemotherapy sensitization, and METTL3 can promote the chemotherapy and radiotherapy sensitivity of pancreatic cancer cells." (PMID 33741902, 2021). "After treated with gemcitabine, only METTL14 was significantly increased in all six pancreatic cancer cell lines, but not METTL3, WTAP, VIRMA, FTO or ALKBH5." (PMID 34458141, 2021). "Furthermore, pancreatic cancer patients with lower METTL3, METTL14, RBMX, FTO, ALKBH5, YTHDF1, and YTHDC1 mRNA expression levels or higher VIRMA, HNRNPA2B1, EIF3A, IGF2BP1, IGF2BP2, and IGF2BP3 mRNA expression levels had significantly poorer OS (P < 0.05)." (PMID 34330301, 2021). "To elucidate the molecular mechanisms responsible for elevated m6A levels in pancreatic cancer, we assessed the expression of the most important m6A regulatory factors (METTL3, METTL14, and WTAP, which form a complex) in the paired cancer and adjacent tissue samples." (PMID 32843065, 2020). "Notably, real-time PCR revealed that METTL3, METTL14, and WTAP were upregulated in pancreatic cancer tissues compared with adjacent, healthy tissues." (PMID 32843065, 2020). "Further study revealed a favorable correlation between the METTL14 levels and N stage (p < 0.01) and American Joint Committee on Cancer (AJCC) stage (p < 0.01), suggesting that METTL14 might regulate the metastasis of pancreatic cancer." (PMID 37215454, 2023). "We observed that METTL14 overexpression decreased the PERP expression levels and increased the colony formation and invasive abilities of pancreatic cancer cells, treated or not with the construct designed for PERP WT overexpression." (PMID 32843065, 2020).
gastric cancer (50 papers, 2019 to 2025). A primary or metastatic malignant neoplasm involving the stomach. "In this study, it was found that METTL14 expression is decreased in gastric cancer and its overexpression is associated with notable repression of growth and invasion of gastric cancer cells in vitro and in vivo." (PMID 38075202, 2024). "Other “writers” (METTL16, WTAP, KIAA1429, RBM15) are likewise overexpressed, suggesting a broader activation of the m6A writing machinery, whereas METTL14 loss correlates with poor differentiation and aggressive behavior suggesting a tumor-suppressive role similar to that seen in gastric cancer." (PMID 41228380, 2025). "In gastric cancer the capabilities of tumorigenesis and invasion from highly expressed METTL14 could be impaired by circORC5 deficiency." (PMID 36875073, 2023). "For instance, METTL14 is downregulated in gastric cancer (GC) tissues, where its low expression is associated with a poorer prognosis." (PMID 40271153, 2025). "For example, m6A modification of circUGGT2 by METTL14 promotes gastric cancer tumorigenesis and cisplatin (DDP) resistance by sponging miR-186-3p and upregulating MAP3K." (PMID 40707002, 2025). "In gastric cancer, METTL14 suppresses stemness, and low METTL14 expression correlates with poor survival." (PMID 41228380, 2025). "Among the available studies, only METTL14 among the m6A modification regulators showed complete tumor suppression in gastric cancer." (PMID 39967906, 2025). "Consistently, METTL14 knockdown promoted gastric cancer cell growth, whereas FTO knockdown (m6A upregulation) reversed the malignant phenotypes." (PMID 36977668, 2023). "For instance, METTL14 was found downregulated and the m6A modification level was low in gastric cancer." (PMID 36977668, 2023). "In gastric cancer, METTL14-mediated m6A modification led to LINC01320 upregulation, which promoted an aggressive phenotype of increased cancer cell proliferation, migration, and invasion via regulating the miR-495-5p/RAB19 axis." (PMID 37029420, 2023). "In gastric cancer and endometrial cancer, knockdown of Mettl14 and decreased m6A levels increased cell migration and invasiveness, establishing METTL14 as a negative regulator of migration and metastasis in these contexts." (PMID 35350378, 2022). "Ectopic expression of METTL14 significantly inhibited gastric cancer cell growth and invasion in vitro and in vivo, while downregulation of METTL14 had the opposite effect." (PMID 36003776, 2022). "METTL14 also inhibits the proliferation and invasion of gastric cancer cells by inhibiting PI3K/AKT/mTOR pathway activation and the EMT." (PMID 35945641, 2022). "Our findings demonstrate that METTL14-mediated m6A modification of circORC5 suppresses gastric cancer progression by regulating miR-30c-2-3p/AKT1S1 axis." (PMID 35164771, 2022). "Advances have been achieved in exploring the crucial roles and molecular mechanisms of METTL14 in multiple types of cancer, especially in gastrointestinal cancer, including liver cancer, colorectal cancer, gastric cancer, and pancreatic cancer." (PMID 35974338, 2022). "Although previous study showed METTL14 is low expression in gastric cancer, but this result just explored in the database and base on the mRNA level." (PMID 34476213, 2021). "A recent study proved knockdown of m6A writer gene METTL14 in gastric cancer cell enhanced proliferation and invasiveness by Wnt and PI3K-Akt signaling." (PMID 33430867, 2021). "In the study, the METTL14 mRNA expression level differences between normal gastric tissues and gastric cancer tissues seemed negligible, while IHC study demonstrated significant difference in METTL14 protein expression between tumor and paratumor samples." (PMID 33314339, 2021). "There is evidence that the PI3K/AKT/mTOR pathway mediates the function of m6A “writers” METTL3 and METTL14 in the progression of gastric cancer and retinoblastoma." (PMID 34088349, 2021).
gastric cancer (continued). "Finally, in what concerns WTAP, it stabilizes the METTL3/METTL14 complex, and its overexpression in gastric cancer predicts poor prognosis and therapy resistance." (PMID 41228380, 2025). "A previous research has reported that METTL14 level was declined in the gastric cancer tissues, and METTL14-mediated m6A modification of circORC5 could inhibit the development of gastric cancer via regulating miR-30c-2-3p/AKT1S1." (PMID 38326804, 2024). "Moreover, METTL14-mediated m6A modification has also been reported to be involved in miR-30c-2-3p regulation in gastric cancer." (PMID 37627217, 2023). "Downregulation of METTL14 increases circORC5 expression in gastric cancer (GC)." (PMID 36854773, 2023). "Similarly, in gastric cancer, METTL14 decreased cell proliferation by negatively regulating the pro-proliferative PI3K/AKT/mTOR pathway, emphasizing the cell-type-specific role of METTL14 in this cellular process." (PMID 35350378, 2022). "In addition, circORC5 can absorb miR‐30c‐2‐3p, reverse the upregulation of miR‐30c‐2‐3p and downregulation of proline‐rich AKT1 substrate 1 (AKT1S1) and eukaryotic initiation factor 4B (EIF4B) induced by METTL14 and regulate the malignant progression of gastric cancer cells." (PMID 38263865, 2024). "A previous study has found that m6A levels of mRNA or total RNA in human gastric cancer (GC) tissues are significantly increased compared to the normal tissues, and METTL14 is a key regulator of m6A disorders in GC." (PMID 38326804, 2024). "Suppression of m6A via METTL14 depletion promoted gastric cancer (GC) cell proliferation through activating Wnt and PI3K-AKT signaling pathways, while upregulation of m6A due to FTO depletion reversed these phenotypical and molecular signaling changes." (PMID 37015927, 2023). "Besides, METTL14 was down-regulated in gastric cancer tissue samples, and its low expression could be a prognostic factor for poor survival in gastric cancer patients." (PMID 36003776, 2022). "Hence, the METTL14/LINC01320/miR-495-5p/RAB19 axis may play a positive role in the development of gastric cancer." (PMID 34288797, 2021). "METTL14 was demonstrated to mediate the m6A modification and the promoted effect of upregulated LINC01320 on gastric cancer progression." (PMID 40069867, 2025). "METTL14 inhibits gastric cancer (GC) cell proliferation and metastasis in vitro and in vivo." (PMID 39827141, 2025). "High expression of METTL3, METTL14, FTO, YTDHF1-2 and IGF2BP1, in gastric cancer, facilitates tumor immune evasion by maintaining the stability and expression of PD-L1 transcripts." (PMID 41228380, 2025). "The regulation of METTL14 on the PI3K-AKT signaling pathway was observed in several malignant tumors such as liver cancer and gastric cancer, which was also validated in our study." (PMID 39054337, 2024). "m6A was found to modulate mTOR and PI3K-AKT signaling pathway in many cancer cells, and the hypermethylation-mediated via METTL14 deactivated the PI3K-AKT and mTOR signaling and suppressed gastric cancer cell proliferation and aggression." (PMID 36743697, 2023). "METTL14 increases m6A of PTEN mRNA, stabilizes PTEN mRNA, increases protein expression, and inhibits the growth and metastasis of gastric cancer." (PMID 35945641, 2022). "METTL14 was downregulated in triple-negative breast cancer (TNBC), esophageal cancer (EC), gastric cancer, osteosarcoma (OS),Wilms tumor, and oral squamous cell carcinoma (OSCC), and low METTL14 expression was related to poor prognosis." (PMID 35115038, 2022). "Mechanistically, METTL14-mediated m6A modification induces the up-regulation of LINC01320, which subsequently affects gastric cancer progression through the miR-495-5p/RAB19 axis." (PMID 34288797, 2021). "The detection of mRNA levels of m6A-modified enzymes (METTL3, WTAP, METTL14, VIRMA, RBM15, FTO, and ALKBH5) in gastric cancer tissues and adjacent tissues showed that the mRNA level of METTL3 was significantly higher in gastric cancer tissues." (PMID 34394353, 2021).
gastric cancer (continued). "However, a glycolysis-promoting role of METTL14 through the repression of LHPP, which inhibits cancer cell metabolism, has been reported in gastric cancer (GC)." (PMID 36859310, 2023). "Collectively, METTL14 alters m6A density of circORC5 to negatively modulate its expression, followed by mediating the miR-30c-2-3p/AKT1S1 axis to induce the occurrence of malignant behavior in gastric cancer." (PMID 36875073, 2023). "Mechanistically, the m6A modification of LHPP mRNA by METTL14 represses its expression; LHPP inhibits the phosphorylation of GSK3b through acetylation and mediates HIF1A to inhibit glycolysis, proliferation, invasion and metastasis of gastric cancer cells." (PMID 35568711, 2022). "Notably, it has been confirmed that METTL14 knockout can activate Wnt and PI3K-Akt signals to promote the growth and invasion of gastric cancer cells." (PMID 35115038, 2022). "However, in gastric cancer cells, LHPP is repressed due to m6A modification mediated by METTL14." (PMID 39138186, 2024). "Knockdown of METTL14 and YTHDF1 could reduce mRNA transcript levels of interferon signaling IFNA/IFNB/IFNG/ISG5, which is involved in the formation of the gastric cancer (GC) microenvironment and suppresses the antitumor immunity mediated by interferon signaling blocking." (PMID 36226062, 2022). "In gastric cancer (GC), previous researches on the expression and role of METTL3 and METTL14 were not consistent, and their specific function and mechanism have remained elusive." (PMID 36866236, 2023).